ACAT1 (acetyl-CoA acetyltransferase 1)
Description:
This is one of the enzymes that catalyzes the last step of the mitochondrial beta-oxidation pathway, an aerobic process breaking down fatty acids into acetyl-CoA. Using free coenzyme A/CoA, catalyzes the thiolytic cleavage of medium- to long-chain 3-oxoacyl-CoAs into acetyl-CoA and a fatty acyl-CoA shortened by two carbon atoms. The activity of the enzyme is reversible and it can also catalyze the condensation of two acetyl-CoA molecules into acetoacetyl-CoA. Thereby, it plays a major role in ketone body metabolism.
Synonyms: ACAT; MAT; THIL; T2
Tractability: Small molecule: a structure with a bound ligand is known; it has a high-quality binding pocket. PROTAC: ubiquitination databases record sites on it; its protein half-life has been measured.
Target class: Enzyme; Transferase
Gene: Protein-coding gene on chromosome 11 (108,116,695 to 108,148,957, forward strand). Ensembl gene ENSG00000075239.
Subcellular location: Mitochondrion
Subcellular location (Human Protein Atlas): Mitochondria
Pathways (Reactome):
Metabolism: Branched-chain amino acid catabolism; Maturation of TCA enzymes and regulation of TCA cycle; Synthesis of Ketone Bodies; Utilization of Ketone Bodies
Disease: Beta-ketothiolase deficiency
Metabolism of proteins: Mitochondrial protein degradation
Gene Ontology:
Molecular function: acetyl-CoA C-acetyltransferase activity; C-acetyltransferase activity; cholesterol O-acyltransferase activity; potassium ion binding; acyltransferase activity; acyltransferase activity, transferring groups other than amino-acyl groups; coenzyme A binding; enzyme binding; identical protein binding
Biological process: acetyl-CoA biosynthetic process; acetyl-CoA catabolic process; coenzyme A biosynthetic process; coenzyme A metabolic process; ketone body catabolic process; L-isoleucine catabolic process; propionyl-CoA biosynthetic process; adipose tissue development; fatty acid beta-oxidation; liver development; metanephric proximal convoluted tubule development; response to hormone; response to starvation
Cellular component: endoplasmic reticulum; extracellular exosome; mitochondrion; mitochondrial matrix
Genetic constraint (gnomAD): Loss-of-function variants: 22 observed, 39.35 expected, observed/expected ratio (o/e) 0.56, 90% interval 0.4 to 0.8. The upper end of that interval is the gene's LOEUF score, 0.8, which puts it in group 3 of 6, group 1 being the genes least tolerant of losing a copy. Missense variants: 437 observed, 502.39 expected, observed/expected ratio (o/e) 0.87, 90% interval 0.8 to 0.94. Synonymous variants: 173 observed, 166.25 expected, observed/expected ratio (o/e) 1.04, 90% interval 0.92 to 1.18.
Gene-disease validity (ClinGen):
ClinGen rates the evidence that ACAT1 causes each of these diseases.
beta-ketothiolase deficiency (autosomal recessive): Definitive.
Homologues: Orthologues: chimpanzee ACAT1 (100% identical), rabbit ACAT1 (92% identical), pig ACAT1 (91% identical), dog ACAT1 (89% identical), guinea pig ACAT1 (88% identical), rat Acat1 (84% identical), mouse Acat1 (84% identical), zebrafish acat1 (77% identical), Drosophila melanogaster Acat1 (62% identical), Caenorhabditis elegans kat-1 (50% identical), Caenorhabditis elegans T02G5.7 (45% identical). Paralogues in human: ACAT2 (41% identical), ACAA2 (38% identical), HADHB (32% identical), ACAA1 (31% identical).
Diseases named in the same sentence as ACAT1 in open-access papers:
ACAT1 is named in the same sentence as 130 diseases in open-access papers, as found by Europe PMC text mining. Sharing a sentence is not in itself a finding about the gene and the disease. The quoted sentences say what the papers report.
atherosclerosis (37 papers, 2009 to 2025). A disease characterized by the build-up of fatty material and calcium deposition in the arterial wall resulting in partial or complete occlusion of the arterial lumen. "The impact of salusins on atherosclerosis is primarily linked to their influence on acetyl-CoA acetyltransferase 1 (ACAT-1) protein expression, which promotes cholesteryl ester accumulation and foam cell formation." (PMID 40332043, 2025). "SOAT1 is involved in atherosclerosis, cholesterol content, glucose and lipid metabolism, study have found that overexpression of ACAT1/2 encoded by SOAT1 can significantly inhibit the differentiation of 3T3-L1 preadipocytes." (PMID 34090334, 2021). "Therefore, the genetic evidences for an association between the ACAT-1 gene and atherosclerosis in humans still needs to been clarified." (PMID 24577316, 2014). "In Soat1 knockout animals, ACAT1 deficiency led to a marked alteration in cholesterol metabolism resulting in massive accumulation of UC, which caused numerous skin and brain lesions, and worsened atherosclerosis." (PMID 24695360, 2014). "Conversely, most evidence supports that decreasing ACAT1 activity actually promotes atherosclerosis, which has been attributed to side effects caused by excess of FC trafficking to the ER membrane, including ER stress, increased synthesis of proinflammatory cytokines, and macrophage death." (PMID 22427949, 2012). "Avasimibe is a drug that has been used in the treatment of atherosclerosis, and it can effectively inhibit ACAT1." (PMID 38169575, 2024). "ACAT1 inhibitor Avasimibe, originally developed for the treatment of atherosclerosis, has been proven to be useful for treating lung cancer and melanoma." (PMID 38534399, 2024). "ACAT1 is an emerging target to treat diverse diseases including atherosclerosis, cancer, and neurodegenerative diseases." (PMID 39273099, 2024). "Positive anti-atherosclerosis activity of ACAT1 inhibitors in mouse and rabbit models supported three multi-center placebo controlled RCTs of two different ACAT1 inhibitors." (PMID 38275616, 2024). "In mouse models of obesity or atherosclerosis, genetic inactivation of Acat1/Soat1 in the myeloid lineage reduces the inflammatory responses seen in macrophages." (PMID 36982689, 2023). "It has been shown that the suppression of atherosclerosis results from the inhibition of foam cell formation from macrophages through the downregulation of the acetyl-coenzyme A acetyltransferase-1 (ACAT-1) enzyme." (PMID 36407198, 2022). "In Apoe-/- mice liraglutide suppressed acyl-coenzyme A cholesterol acyltransferase 1 (Acat1) expression, foam cell formation and decreased atherosclerosis, and inhibited progression of early-onset atherosclerosis lesions in a GLP1R-dependent fashion." (PMID 33440821, 2021). "Pharmacological inhibition of ACAT1 increases plaque formation in mouse and rabbit models of atherosclerosis." (PMID 31653058, 2019). "Our results showed that overexpression of salusin-α increased the expression of positive regulators of atherosclerosis (ABCA1 and ABCG1) and inhibited negative regulators of atherosclerosis (ACAT1 and CD36)." (PMID 30105261, 2018). "In mice, ACAT1 small molecule inhibition, genetic knockout, and macrophage-specific deletion reduce atherosclerosis pathology." (PMID 30283400, 2018). "Several studies suggest an important role of Acyl-CoA: cholesterol acyltransferase-1(ACAT-1) in the development of atherosclerosis." (PMID 29179498, 2017). "Studies revealed that LD-associated proteins ACAT1 and ABCA1 regulating cholesterol esterification play crucial roles in atherosclerosis." (PMID 28662670, 2017). "Partial inhibition of ACAT-1 reduced atherosclerosis, effectively suggesting that ACAT-1 inhibitors prevent atherosclerosis in a dose-dependent manner." (PMID 24577316, 2014). "Studies have demonstrated that ACAT-1 plays an important role in atherosclerosis and is expressed at elevated levels in foam cells located within atherosclerotic lesions." (PMID 24405662, 2013).
atherosclerosis (continued). "Data from in vivo studies indicate that the form of ACAT in macrophages, ACAT1, contributes to foam cell formation in the arterial wall and the development of atherosclerosis." (PMID 22934038, 2012). "Excess cholesterol ester production via ACAT1 and decreased cellular cholesterol efflux via ABCG1 are two pathways that may contribute to atherosclerosis caused by Pg-LPS." (PMID 38532421, 2024). "Avasimibe is an inhibitor of ACAT1 and has been used to treat atherosclerosis." (PMID 38169575, 2024). "Given its crucial role in cholesterol metabolism, ACAT1 has emerged as a therapeutic target for treating a broad spectrum of diseases, including atherosclerosis, cancer, dyslipidemia, and neurodegenerative diseases like Alzheimer’s disease (AD) and Niemann-Pick Type C disease (NPCD)." (PMID 39273099, 2024). "In addition, in a different mouse model, myeloid Acat1/Soat1 knockout (KO) attenuates pro-inflammatory responses in macrophages and protects against atherosclerosis." (PMID 36982689, 2023). "Mouse studies portray that reduction in myeloid ACAT1 alleviates diet-induced atherosclerosis." (PMID 33841127, 2021). "The present study provides the first evidence that β-endorphin stimulates atherosclerosis by increasing the inflammation in ECs and macrophages, mediating oxLDL-induced foam cell formation in association with CD36 and ACAT-1 upregulation, and inducing migration and apoptosis in VSMCs." (PMID 32308678, 2020). "Previous studies also demonstrated that ACAT-1 was involved in the formation of atherosclerotic plaques, and thus might be a promising target for atherosclerosis and hypercholesterolemia treatment." (PMID 29179498, 2017). "Taken together, it is debatable whether the development of macrophages into cholesterol ester–rich foam cells promotes or inhibits atherosclerotic lesion development; the effects of ACAT-1 on atherosclerosis remain to be further investigated." (PMID 29179498, 2017). "The absence of ACAT-1 was shown to attenuate atherosclerosis but cause meibomian gland atrophy and cutaneous xanthomatosis in a mouse model." (PMID 23734839, 2013). "In the present study, we showed that the C variant of ACAT-1 rs1044925 SNP could increase serum HDL-C and ApoAI levels in the male subjects with hypercholesterolemia, which may play a protective factor for atherosclerosis." (PMID 22243772, 2012). "In addition, genes Soat1 and Soat2 are known to encode ACAT1 and ACAT2 enzymes in catalyzing the formation of cholesteryl esters, an important process during atherosclerosis formation." (PMID 19835623, 2009). "However, the role of ACAT-1 in atherosclerosis is currently inconsistent in different studies." (PMID 29179498, 2017). "Therefore, the role of ACAT-1 in atherosclerosis remains to be clarified." (PMID 24577316, 2014). "However, whether ACAT-1 inhibition will serve as an effective drug target for controlling atherosclerosis is under debate." (PMID 24577316, 2014). "Hence it was tested whether partial inhibition of ACAT1 and ACAT2 (expressed in liver and intestine) activities reduces atherosclerosis development in apoE-deficient mice and avoids toxicity." (PMID 22934038, 2012). "Avasimibe (Ava) is an acetyl-CoA acetyltransferase 1 (ACAT1) specific inhibitor and an established medicine for atherosclerosis, owing to its excellent and safe anti-inflammation effects in humans." (PMID 35222024, 2022). "The expression of positive regulators of atherosclerosis (ABCA1, ABCG1) was higher in the P group than that in the RP group (P < 0.05), and the opposite effect was observed for negative regulators (ACAT1, CD36)." (PMID 30105261, 2018). "In hyperlipidemic mice, deletion of ACAT1 results in both impairment of ABCA1 dependent cholesterol efflux and elevated atherosclerosis." (PMID 28662670, 2017).
atherosclerosis (continued). "Therefore, the possible mechanism by which ACAT-1 gene variants protect against atherosclerosis is that inhibiting ACAT-1 may directly or indirectly diminish foamy macrophage formation, thus further reducing the incidence of atherosclerosis." (PMID 24577316, 2014). "They analyzed the promoter methylation of ATP binding cassette subfamily A member 1 (ABCA1), TIMP metallopeptidase inhibitor 1 (TIMP1), and acetyl-CoA acetyltransferase 1 (ACAT1) and observed significant alterations in the peripheral blood of atherosclerosis patients." (PMID 31649728, 2019). "In contrast, systemic ACAT1 deficiency ApoE−/− and LDL−/− mice does not affect atherosclerosis, but these mice develop dermal xanthomas and form cholesterol deposits in the brain." (PMID 31653058, 2019). "In addition, this protein is also involved in the prevention of macrophage foam cell formation by downregulating acetyl-coenzyme A acetyltransferase 1 (ACAT1), thereby affecting atherosclerosis." (PMID 30105261, 2018). "ABCA1, ABCG1, ACAT1, and CD36 are positive or negative regulators of atherosclerosis." (PMID 30105261, 2018). "This demonstrates that low ratio of n-6 to n-3 inhibits the formation of the foam cells as the quantity of cholesterol uptake via CD36 and biosynthesis via ACAT1 is less than the cholesterol efflux via ABCA1, which co-regulate to inhibit the development of the atherosclerosis." (PMID 29801502, 2018). "Therefore, pharmacological inhibition of ACAT is expected to suppress foam cell formation in arterial walls by suppressing macrophage ACAT-1 and cholesterol absorption by suppressing intestinal ACAT-2, thereby inhibiting atherosclerosis." (PMID 24577316, 2014). "In the present study, we did not determine the association of ACAT-1 rs1044925 SNP and the level of cholesterol efflux, HDL particle sizes, as well as the extent of atherosclerosis." (PMID 22243772, 2012). "However, nCEH overexpression alone without decreasing the expression of ACAT1 and stimulation of cholesterol efflux was not enough to protect against atherosclerosis." (PMID 26493158, 2016).
prostate carcinoma (25 papers, 2012 to 2025). A carcinoma that arises from epithelial cells of the prostate gland. "At the same time, through the GEPIA database, we found that high ACAT1 expression was associated with a poor prognosis in patients with prostate cancer (P = 0.047)." (PMID 36517760, 2022). "Further, elevated ACAT1 expression is associated with reduced time to biochemical recurrence of prostate cancer as well as progression-free and overall survival." (PMID 35033184, 2022). "A study performed in prostate cancer cells demonstrated that the inhibition of ACAT1 significantly reduces the CE level." (PMID 40723223, 2025). "In prostate cancer, ACAT1 inhibited autophagy or oxidative stress by preventing FUS from transcribing LC3B or scavenging ROS, thereby promoting tumorigenesis." (PMID 38817856, 2024). "In prostate cancer, the inhibition of ACAT1 with Avasimibe has demonstrated significant therapeutic effects." (PMID 38610991, 2024). "ACAT1 inhibitors disrupt the biogenesis of CE-rich LDs, reducing cancer proliferation and aggressiveness in prostate cancer." (PMID 39232826, 2024). "It was discovered that MAPK pathway activity was enhanced by SIRT5 via ACAT1, thereby boosting the migration, invasion, and proliferation ability of prostate cancer cells." (PMID 38817856, 2024). "The altered expression level of ACAT1 has been reported in clear renal cell carcinoma, prostate cancer and glioblastoma and the understanding of the molecular mechanisms underlying its oncogenic role would still require further research." (PMID 36816175, 2023). "SIRT5 is also significantly expressed in prostate cancer, where it activates acetyl-CoA acetyltransferase 1 (ACAT1) and induces a mitogen-activated protein kinase (MAPK) pathway." (PMID 36980194, 2023). "In contrast, an elevated expression of ACAT1 was reported in prostate cancer tissues compared to the adjacent benign tissues, and high levels of ACAT1 expression were observed in high grade and advanced prostate cancer." (PMID 36816175, 2023). "As presented on the Gene Expression Profiling Interactive Analysis database, acetyl-CoA acetyltransferase 1 (ACAT1) acts as a prostate cancer-promoting factor." (PMID 36517760, 2022). "We conducted immunohistochemical analysis of 57 clinical samples and in vitro and in vivo experiments using a mouse model and plasmid constructs to determine the expression of ACAT1 in prostate cancer." (PMID 36517760, 2022). "ACAT1 expression in prostate cancer tissues is considerably higher than that in normal tissues, leading to a poor prognosis in patients with prostate cancer." (PMID 36517760, 2022). "Here, we aimed to study the role of the ACAT1-FUS complex in prostate cancer and identify new targets for the diagnosis and treatment of the disease." (PMID 36517760, 2022). "Nonetheless, we demonstrated that the ACAT1-FUS complex plays a crucial role in prostate cancer development, which provides insights into the development of new therapeutic strategies by targeting or inhibiting the formation of this complex in prostate cancer." (PMID 36517760, 2022). "The authors further demonstrated that SIRT5 decreased the protein levels of acetyl-CoA acetyltransferase 1 (ACAT1), a promoter of prostate cancer." (PMID 36291902, 2022). "Here, we aimed to study the role of the ACAT1-fused in sarcoma (FUS) complex in prostate cancer and identify new targets for the diagnosis and treatment of the disease." (PMID 36517760, 2022). "Here, we showed that ACAT1 expression was higher in prostate cancer tissues, especially in high-grade tumors with Gleason scores of 8 and 9 than in normal tissues." (PMID 36517760, 2022). "Although the mechanism by which ACAT1 promotes prostate cancer has been demonstrated, the mechanism by which ACAT1 prevents FUS from entering the nucleus needs to be further explored." (PMID 36517760, 2022).